TNF (tumor necrosis factor)
Diseases named in the same sentence as TNF in open-access papers (continued):
Sharing a sentence is not in itself a finding about the gene and the disease.
Sepsis (continued). "Indeed, in the setting of Gram-negative bacteremia and sepsis, the onset of myocardial depression and ventricular dilatation following an outflow of cytokines (IL1β, IL-6, and TNFα), nitric oxide, and endotoxins has been reported." (PMID 37756092, 2023). "In comparison to the sham group, the sepsis group had significantly higher levels of TLR-4, IL-6, TNF-α, MIF, F2-isoprostane, caspase-3, cTn-I, and CK-MB, while the pre-treated group with Xanthohumol had significantly lower levels (p<0.05) of these markers than the sepsis group." (PMID 37900069, 2023). "PKCδ inhibition was also shown to significantly reduce TNF-α-mediated hyperpermeability, decrease transendothelial electrical resistance (TEER), and interrupt tight junction expression in vitro in activated HBMVECs and rat brain in vivo 24 h after cecal ligation and puncture (CLP) induced sepsis." (PMID 37974282, 2023). "In sepsis-induced ALI, intranasal Curcumin could significantly reduce the expression of oxidative stress marker (e.g., nitric oxide (NO) and malondialdehyde (MDA)) and inflammatory cytokines (e.g., TNF-α)." (PMID 37700323, 2023). "Currently, there are no drugs specifically approved to treat sepsis, although some drugs were (unsuccessfully) trialled that target particular inflammatory pathways, for example, Cytofab, a drug made by AstraZeneca, targeting TNF-α." (PMID 37761018, 2023). "The anti-inflammatory function of GLP1-RAs was suggested to be through the inhibition of tumor necrosis factor alpha (TNFα) and decreases in vascular cell adhesion protein 1 (VCAM-1), intercellular adhesion molecules 1 (ICAM-1) and E-selectin expression in an animal sepsis model." (PMID 36932379, 2023). "Furthermore, among patients whose dose was escalated, the adjusted odds of experiencing the composite adverse outcome of infection, sepsis, or IBD-related hospitalization were higher for those treated with an anti–TNF-α treatment (adalimumab or infliximab) than for those treated with vedolizumab." (PMID 38028955, 2023). "Here, after the induction of sepsis, IL-10 levels were attenuated in OSMR KO mice following the induction of FIP, as were the levels of the pro-inflammatory cytokines IL1β, IL-6, TNF, and KC, which may reflect a more balanced attenuation of inflammation with improved survival." (PMID 36831019, 2023). "Furthermore, Ticagrelor was found to reduce tissue cytokine levels of the lung (IL-1, TNF a, IL-6, F2 isoprostane, GPR 17, MIF) in male mice during CLP-induced polymicrobial sepsis by modulation of pro-inflammatory and oxidative stress cascade signaling pathways." (PMID 37675176, 2023). "Importantly, we also showed for the first time that persistent changes in Tie-2, Flt-1, bFGF, IL-7, and TNFα were uniquely seen in patients following recovery following COVID-19, but not in patients recovering from severe sepsis." (PMID 36844209, 2023). "In our study, we found that injecting parenteral ω-3 PUFA solutions reduced IL-1β, TNF-α, IL-6, IL-10, IFN-γ, and IL-17 levels and hindered the secretion of multi-organ injury markers induced by CLP treatment, indicating the protective role of ω-3 PUFAs in sepsis." (PMID 36694426, 2023). "Therefore, the immunotherapeutic strategies of sepsis in the past were mainly to inhibit the inflammatory response and block the pro-inflammatory cytokines such as PAMPs, Toll-like cytokines (TLRs), TNF-α, IL-6, etc., but the results were not as expected." (PMID 37292207, 2023). "Independent of sepsis IP, TNF-α levels may also be influenced by a variety of other factors, such as: type of LPS used, blood volume, incubation conditions, and LPS concentration." (PMID 36825018, 2023). "Finally, since only TNF-α was measured using a standardized IFA, the release of other Th-1 and pro-inflammatory mediators known to be impaired in sepsis, as well as mHLA-DR expression, need to be evaluated using a similar assay in a larger multicenter LD cohort." (PMID 37965258, 2023).
Sepsis (continued). "The original hypothesis was that CLX and IFX would protect against sepsis through their anti-inflammatory and antioxidant effects, which were speculated to involve the modulation of two pathways that are known to be upregulated during sepsis; the COX-2 and TNF-α pathways, respectively." (PMID 35884918, 2022). "Besides, the serum levels of TNF-α, IL-1β, and IL-6 in the γ3-RBCNPs group were significantly lower than those in PBS groups, indicating that γ3-RBCNPs reduced systemic inflammatory response in mice with sepsis." (PMID 35783411, 2022). "Results of this research showed that TNF-α and neutrophils decreased gradually in the CLP and LBP groups in contrast to a persistent increase of IL-10, suggesting that the body was dominated gradually by anti-inflammatory reactions and sepsis entered the status of immunosuppression." (PMID 36248408, 2022). "In addition, silymarin (100 mg/kg, i.p.)enhanced overall survival following sepsis compared to septic group (80% vs. 20%) in rat model, as well as improved hepatic and renal function parameters and decreased MDA, nitrite/nitrate, IL-6, and TNF-α levels." (PMID 36588685, 2022). "The silencing of miR-10a can inhibit sepsis-induced liver injury in rats, suggesting a possible protective role, with the downregulation of the TGF-β1/Smad pathway and the inhibition of the expression of IL-6, ROS and TNF controlling inflammatory development in septic rats." (PMID 36012630, 2022). "Targeting therapy with anti-TNF-α blockade and a temporary withdrawal of traditional immunosuppressants may be among effective and safe therapeutic options of OLT-aGVHD for those with severe sepsis." (PMID 36059444, 2022). "However, drugs targeting TNF-α, IL-1β, or toll-like receptors have not achieved satisfactory clinical results in improving the survival rate of patients with sepsis." (PMID 36209190, 2022). "In splenocytes, TNF-α secretion after LPS stimulation was also significantly attenuated until 24 h after sepsis (nearly no response), and then fully recovered on day 7 after sepsis." (PMID 35743025, 2022). "The AST could affect the TNF, PI3K, and MAPK pathway cascade responses centred on IκBα and NF-κB, attenuate the expression of IL-6 and MMP9, and interfere with the inflammatory response during sepsis." (PMID 35399630, 2022). "Since we found that HDAC6 inhibition seems effective in dampening the inflammatory response in vitro and plays a role in sepsis in vivo, we next focused on ITF3756 and asked whether the inhibitor could impinge on the TNF-α induced pro-inflammatory program in monocytes." (PMID 35592335, 2022). "However, the fact that NewSTAR2 and other TNFR2 agonist used in the literature do not trigger sepsis like symptoms, the major effect of TNF administration, this possibility is systemically obviously irrelevant." (PMID 35769484, 2022). "Similarly, the previous studies showed that LNT reduces the activation of NF-κB and inhibits the production of pro-inflammatory cytokines IL-1β, TNF-α, IL-8 in chondrocytes, LNT intervention improves hepatic cell morphology by the decreased activity of NF-κB signal in rat’s liver with sepsis." (PMID 35313999, 2022). "This sequence of pro-inflammatory cytokines followed by release of anti-inflammatory cytokines is also seen in sepsis and acute inflammatory conditions but in contrast to sepsis, there is no preceding or accompanying increase in TNF-α in moderate acute exercise." (PMID 34991697, 2022). "However, data regarding the therapeutic effects of triple cytokine (TNF-α, IL-1β, and IL-6) inhibitions versus single cytokine (TNF-α) inhibition against sepsis remain lacking." (PMID 35337084, 2022). "Decreased TNF-α secretion after LPS stimulation has also been noted in sepsis non-survivors." (PMID 36140385, 2022).
Sepsis (continued). "Similar results were shown in models of acute lung injury after sepsis (decreased TNF-α, IL-1β, and IL-6 secretion) and paraformaldehyde injury (decreased cell death, MyeloPeroxidase activity, parenchymal vascular permeability, TNF-α and IL-6 secretion, and increased IL-10 secretion)." (PMID 35874678, 2022). "This study tested the hypothesis that lack of TNF shedding from peripheral leukocytes would mitigate sex-specific differences in the cardiac response to early normovolaemic sepsis." (PMID 35723764, 2022). "However, SS patients did not overexpress TNF-α compared to both control groups, although the levels were higher in SS compared to sepsis." (PMID 35327327, 2022). "6-Gingerol-treated mice also displayed lower mortality in polymicrobial sepsis induced by CLP by enhancing bacterial clearance in the peritoneum, blood, and organs (liver, spleen, and kidney) while also suppressing the generation of TNF-α and IL-6 in TLR2 and/or TLR4-stimulated macrophages." (PMID 36588685, 2022). "However, clinical studies have reported that anti-TNF-α antibody treatments have not had beneficial effects for patients with sepsis." (PMID 34439967, 2021). "Interestingly, it has been reported that a difference in the IL-10-to-TNF-α ratio was seen in patients with severe sepsis, with nonsurvivors having a ratio of >4.5 48 h after admission." (PMID 34152806, 2021). "In addition, the concentrations of pro‐inflammatory cytokines TNF‐α, IL‐1β, IFN‐γ and IL‐6 in circulation were prominently repressed after wogonin treatment in these two types of sepsis mice, with the levels of these cytokines gradually decreased as the dose of wogonin increased." (PMID 33982381, 2021). "Initially, sepsis was induced by performing CLP in mice, after which the mouse models presented significant myocardial depression, injury and inflammation, showing as decreased MAP, LVSP and ±dp/dtmax values, and increased cTnI, CK-MB, TNF-α, IL-6, IL-1β and NO levels in mice." (PMID 33645622, 2021). "The expression level of NF-κB and TNF-α was significantly higher in LPS-induced H9c2 cardiomyocytes, suggesting that the expression of NF-κB/TNF-α might be related to inflammatory response and apoptosis of H9c2 cells during sepsis." (PMID 34938184, 2021). "Interestingly, SENEX is a TNFα-sensitive gene and in vitro treatment by low concentration of TNFα prompts the endothelial downregulation of this gene leading to apoptosis, confirming SENEX as a promising target in the early prevention of sepsis-induced endothelial senescence." (PMID 34851467, 2021). "Sepsis induction reduced NF-κB and SOD2 protein expression but increased their acetylation, and this was accompanied by an increase in proinflammatory cytokines (TNF-α/IL-6/IL-10) and oxidative stress (indicated by reduced SOD2 activity, GSH content, GSH/GSSG ratio, and CAT activity)." (PMID 33790896, 2021). "Plasma levels of TNF-α are low in patients admitted in ICU later after infection, which might explain, at least in part, why TNF-α blockade using neutralizing monoclonal antibody failed to improve sepsis outcome in randomised trials." (PMID 33439360, 2021). "Some latest studies showed that the expression level of TNF-α was significantly higher in LPS-induced H9c2 cardiomyocytes, suggesting that the expression of NF-κB/TNF-α might be related to inflammatory response and apoptosis of H9c2 cells during sepsis." (PMID 34938184, 2021). "For example, previous studies have shown that DEX could suppress the inflammatory response by inhibiting the production of proinflammatory cytokines (tumor necrosis factor (TNF)-α and interleukin (IL)-1β, IL-6), thus protecting against sepsis-induced ALI or acute kidney injury." (PMID 34747306, 2021). "In an experimental model of sepsis, pretreatment of mice with ANP resulted in improved survival of mice after LPS challenge, which may be due to the potent inhibitory effect of ANP on LPS and TNF-α-induced increase in endothelial cell permeability." (PMID 34109195, 2021).
Sepsis (continued). "For co-expression, “TNF signaling pathway,” “NF-kappa B signaling pathway,” “Jak–STAT signaling pathway,” and “Apoptosis” were enriched, suggesting that TUCPs could function in these pathways in sepsis-induced myocardial depression." (PMID 33832434, 2021). "We established both CLP- and LPS-induced sepsis models in mice and verified that SPION-MSCs significantly improved the symptoms of sepsis, such as increasing the survival rate of mice, reducing the levels of serum TNF-α, IL-6, ALT and AST, and relieving liver tissue damage." (PMID 34627385, 2021). "The Sepsis + ARDS group had a greater respiratory rate, a lower PaO2/FiO2, a greater SOFA score, and higher levels of lactate (LAC), procalcitonin (PCT), C-reactive protein (CRP), interleukin 6 (IL-6), tumor necrosis factor α (TNFα), IL-10, and FGF21 (all P < 0.05)." (PMID 34154595, 2021). "Also, cytokine levels (TNF alpha and IL-6) were highest in the CRAB sepsis than CSAB sepsis." (PMID 34493028, 2021). "It was reported that acupuncture at ST36 significantly decreased alanine aminotransferase (ALT) and aspartate aminotransferase (AST), attenuating sepsis-induced hepatic injury by reducing the tissue water content of liver and suppressing hepatic inflammatory cytokines (iNOS, MPO, and TNF-α)." (PMID 32215037, 2020). "Although neutralization of TNF-α or interleukin 1 β (IL-1β) did not reduce mortality in sepsis trials, experimental and clinical data have shown that these proinflammatory cytokines with specific relevance for innate immune functions are important mediators of severe sepsis." (PMID 32670276, 2020). "In this study, we have shown that SGC-CBP30 attenuated circulating HMGB1 levels even when the treatment was started at 8 h after sepsis modeling, and that HMGB1 induced the release of TNF-α, suggesting that CBP bromodomain might function as a regulator in controlling HMGB1." (PMID 33603756, 2020). "In vitro a significant reduction for IL-6, IFN-y, MIP-1α, C5a, HMGB-1, procalcitonin and S100-A8, but not of TNF-α could be achieved in blood samples with sepsis-like high cytokine levels by binding to CytoSorb® hemoadsorbent polystyrene beads." (PMID 33141843, 2020). "Also, acupuncture therapies were reported as being capable of decreasing secretion of IL-6, high mobility group protein box-1 (HMGB1), TNF-α, IL-10, and interferon-γ (IFN-γ), demonstrating acupuncture at ST36's potential of reducing inflammation in sepsis." (PMID 32215037, 2020). "However, insights gained from this clinical trial on TNF-α inhibition does not support a simple concept of hyper-inflammation induced by TNF driving the pathogenesis of sepsis." (PMID 33679715, 2020). "However, TNFR1 KO mice still present some daily differences in response to endotoxin, evidencing that TNF-α signaling through TNFR1 is not the only modulatory pathway responsible for the daily variation in the response to sepsis." (PMID 32226779, 2020). "While blockade of TNF or its receptor, or mAb to C5 has been effective in patients with paroxysmal nocturnal hemoglobinuria or myasthenia gravis, similar interventions have not been successful in the setting of sepsis in mice or humans." (PMID 33425963, 2020). "We show here that zoledronate readily induces upregulation of HLA‐DR, CD40 and CD64 on monocytes from both healthy controls and sepsis patients, which could be abrogated by neutralising the pro‐inflammatory cytokines interferon (IFN)‐γ and tumour necrosis factor (TNF)‐α in the cultures." (PMID 31606902, 2020). "This analysis showed that immune suppression, as reflected by a reduced capacity of blood leukocytes to produce TNF-α, could be detected in sepsis and non-sepsis patients to a similar extent." (PMID 32477337, 2020). "Moreover, lack of TNF-α signaling, as in TNF-α receptor (TNFR) deficient (KO) mice or generated by soluble TNFR administration, induces higher resistance to sepsis." (PMID 32226779, 2020).
Sepsis (continued). "In mice subjected to CLP and fed a HFD, but not treated with Candida, sepsis were more severe than regular diet mice as determined by survival, organ injury (serum creatinine and alanine transaminase), serum cytokines (TNF-α and IL-6), gut leakage by FITC–dextran and endotoxemia, but not serum BG." (PMID 33101279, 2020). "Unlike TNF-α, whose synthesis and secretion are inflammasome-independent, production of IL-1β and IL-18, which requires inflammasome-dependent caspase-1 activation, was more abundant in the serum of Dox-induced iUVRAGFS mice than littermate control in sepsis." (PMID 31831743, 2019). "In the present study, TNF-α only exhibited a slight upward trend, while the expression of PDGFR-β was significantly increased following treatment with LPS, which may be affected by multiple factors related to sepsis." (PMID 31523178, 2019). "In severe sepsis and ARDS, substantive cell injuries and damage-associated molecular pattern release take place, which, according to our data, would lead to secretion of TNF in the MV-enclosed, rather than soluble, form." (PMID 30776316, 2019). "Moreover, for a model rat carrying sepsis, an MCT diet could significantly reduce the expression levels of pro-inflammatory cytokines and chemokines (TNF-α, IL-18, macrophage inflammatory protein-2, and MCP-1) in the ileum and Peyer’s patches." (PMID 31182969, 2019). "In the cecal ligation and puncture (CLP)-induced sepsis model, MALAT1 expression is significantly upregulated, which in turn aggravates cardiac dysfunction and inflammation by activating p38 MAPK/NF-κB, resulting in increased TNF-α, IL-1β, IL-6, IL-10, IL-17 and IFN-γ." (PMID 31711545, 2019). "However, anti-TNF treatment did not change these parameters, suggesting that TNF is not affecting directly the coagulation cascade, as observed in sepsis." (PMID 31139194, 2019). "In a murine model of sepsis induced by caecal ligation and puncture, DHA-derived resolvin D1 decreased the bacterial load in the blood and peritoneum, decreased lung injury, decreased plasma concentrations of TNF, IL-6, IL-10, and interferon-γ, and improved survival." (PMID 31072006, 2019). "TNF-α neutralization did not reduce mortality in a CLP sepsis model." (PMID 31480519, 2019). "Recent study reported that lncRNA-HOTAIR increase the release of TNF-α in the cardiomyocytes of LPS-induced sepsis mice by activating NF-κB through the phosphorylation of NF-κB p65 subunit, suggesting that lncRNA may plays a role in ALI through the regulation of TNF-α." (PMID 30979832, 2019). "At the same time, the serum IL-6 and TNF-α levels which are early biomarkers for sepsis also reached a maximum at around 4 h and 2 h after the injection, respectively (p < 0.05), indicating that TSLP may be an early biomarker for sepsis." (PMID 31480519, 2019). "Whereas, IL-1 and TNF-α pathways have been investigated as a strategy to improve sepsis outcome, by studying the impact of humoral signals from leukocytes on endothelial cells, we observed a stronger enrichment of IFN-α/β and IFN-γ signaling than IL-1 and TNF-α signaling in endothelial cells." (PMID 31708927, 2019). "During sepsis, endotoxin lipopolysaccharides (LPS) activate toll-like receptor 4 (TLR4) signaling pathway and further induce translocation of nuclear factor-kappa B (NF-kappa B) to modulate expression of pro-inflammatory genes, including TNF-α, IL-6, and IL-1β." (PMID 30083155, 2018). "In patients with sepsis, serum tenascin-C levels were significantly positively correlated with SOFA scores (P = 0.011), serum creatinine (P = 0.006), C-reactive protein (CRP) (P = 0.001), interleukin-6 (IL-6) (P < 0.001), and tumor necrosis factor α (TNF-α) (P = 0.026)." (PMID 30442110, 2018). "Additionally, RA patients were treated with the combination of IL1 and TNF neutralizing drugs but this therapy did not have added value, although it seemed promising in preclinical sepsis models and in acute myeloid leukemia." (PMID 29751683, 2018).